MTOR (mechanistic target of rapamycin kinase)
Diseases named in the same sentence as MTOR in open-access papers (continued):
Sharing a sentence is not in itself a finding about the gene and the disease.
neurodevelopmental disorder (continued). "In addition to the neurodevelopmental disorders and the cancer predisposition syndromes caused by mutations in ATR, ATM, mTOR, and their regulated pathways, studies have shown that mutations in human Tel2 may also contribute to the development of sessile serrated adenomas and breast cancer." (PMID 37175973, 2023). "While there have been efforts to comprehensively describe known metabolic changes in other neurodevelopmental disorders, no such effort exists for MCD associated with mTOR pathway gene mutations (the most common cause of MCD; mTORopathies')." (PMID 41788546, 2026). "Although mTOR-associated impaired autophagy has previously been reported in neurodevelopmental disorders, there is lack of information about the dysregulation of mTOR-independent autophagy in neurodevelopmental disorders." (PMID 34183057, 2021). "In a disease such as TSC, early intervention may improve long-term performance in school, social and professional life and TSC could serve as a model for targeted, mechanism-driven approaches for related neurodevelopmental disorders with and without dysregulated mTOR signaling." (PMID 39762914, 2025).
hematological malignancies (69 papers, 2008 to 2025). "Moreover, the PI3K/Akt/mTOR axis is associated with several mutations in hematological malignancies." (PMID 37958470, 2023). "Moreover, hyperactivation of mTOR is a hallmark of many hematological diseases and provides a strong rationale for the use of mTOR inhibitors (mTORi), such as Rapalogs." (PMID 33489922, 2020). "Since overexpression of mTOR has been extensively associated with increased proliferation rates in hematological malignancies, exploiting the aberrant pathway may be a potential approach to further increase the size differential between normal and neoplastic cells." (PMID 26490657, 2015). "Emerging evidence supports a complex functional interaction between the Hh/Gli and PI3K/Akt/mTOR pathways in several cancer types, such as melanoma, prostate cancer, glioma, and hematologic malignancies." (PMID 41439992, 2025). "In this review, we gathered the latest knowledge about the role of the PI3K/Akt/mTOR pathway in blood cancer, pharmacological inhibitors of the pathway, and their application in hematologic malignancies treatment." (PMID 37958470, 2023). "While there haven’t been many studies on the effect of polyphenols on the PI3K/Akt/mTOR pathway in hematological malignancies, a few done shows their efficacy." (PMID 36386899, 2022). "The PI3K/Akt/mTOR pathway is seen as a prime target because of its frequent activation in many cancers including hematological malignancies." (PMID 36386899, 2022). "Our study thus illustrates how hyperactivated AKT/mTOR signaling exerts distinct impacts on hematological malignancies vs. solid tumors." (PMID 35243242, 2022). "Aberrant activation of the PI3K/AKT/mTOR signaling pathway contributes to oncogenesis in solid tumors and hematologic malignancies." (PMID 36039910, 2022). "As aberrant activation of PI3K/AKT/mTOR signaling contributes to oncogenesis in solid tumors and hematologic malignancies, there is interest in developing therapies targeting components of this pathway." (PMID 36039910, 2022). "PIM kinases have emerged as important effectors and mediators to mTOR activity in hematologic malignancies." (PMID 34503111, 2021). "The link between HSP90 inhibition and PI3K/AKT/mTOR signaling suppression has been previously reported in a number of solid and hematological malignancies, and our results support these findings." (PMID 35095481, 2021). "The mechanistic target of rapamycin (mTOR) is a kinase whose activity is elevated in hematological malignancies." (PMID 34408976, 2021). "PI3K/AKT/mTOR signaling is known to play a central role in up regulating cell proliferation, survival, and drug resistance in numerous hematologic malignancies." (PMID 32993794, 2020). "We also provide our perspective on the evolution of this field, as the application and efficacy of mTOR inhibitors becomes more widely recognized in the field of blood disorders." (PMID 33489922, 2020). "Rapalogs, as inhibitors of mTOR, have demonstrated clinical value, not only in the regulation of abnormal immune responses found in benign hematologic diseases, but also for the treatment of hematological malignancies." (PMID 33489922, 2020). "Over the years, several small molecules that target the PI3K/Akt/mTOR signaling pathway have been investigated, showing potential therapeutic efficacy in hematologic malignancies, alone or in combination with chemotherapeutic drugs." (PMID 30110936, 2018). "Many studies have confirmed that aberrant PI3K/Akt/mTOR signaling is significantly related to progression of various solid tumors and hematological malignancies, and we found that EPS8 expression level were downregulated after the Akt signals were blocked." (PMID 29357910, 2018). "Most of these miRNAs have been reported to regulate the expression of key genes in the PI3K/Akt/mTOR pathway, and they are involved in the development and pathogenesis of hematological malignancies." (PMID 30110936, 2018).
hematological malignancies (continued). "Targeting the PI3K/AKT/mTOR pathway is an emerging strategy for the treatment of hematological malignancies." (PMID 29997504, 2018). "Because mTOR signaling has proved to be crucial to cell proliferation and survival in hematological malignancies, mTOR inhibitors are being investigated in a myriad of preclinical and clinical trials." (PMID 28186963, 2017). "Numerous PI3K inhibitors including pan-PI3K, isoform-selective and dual PI3K/mammalian target of rapamycin (mTOR) inhibitors have exhibited favorable preclinical results and entered clinical trials in a range of hematologic malignancies and solid tumors." (PMID 28592260, 2017). "Evidence exists that PLCβ1 interconnected with PI3K/AKT/mTOR signaling in solid tumors and hematological malignancies." (PMID 26614510, 2016). "Recently, the mTOR signaling pathway has received much attention as a potential target in hematological malignancies." (PMID 26189041, 2015). "All of these agents remain under active preclinical study, and combination approaches of PI3K/mTOR pathway inhibitors and other signal transduction inhibitors in hematologic malignancies are also in progress in the laboratory." (PMID 24904824, 2014). "The upregulation of this protein has been shown in solid tumors and hematologic malignancies, and therefore, inhibition of the mTOR protein can limit malignancy growth for patients refractory to other treatments." (PMID 25515347, 2014). "Inhibitors of the mechanistic target of rapamycin (mTOR) hold promise for treatment of hematological malignancies." (PMID 24586420, 2014). "A smaller number of mainly early phase trials evaluating next-generation PI3K/mTOR pathway inhibitors in adults with relapsed/refractory hematologic malignancies are currently open." (PMID 24904824, 2014). "The current repertoire of PI3K/mTOR pathway inhibitors in development and clinical trials to date are described with emphasis upon pediatric hematologic malignancies." (PMID 24904824, 2014). "Ultimately, the direct targeting of mitochondria and the simultaneous deregulation of the IGF1R-Akt-mTOR signaling cascade make shikonin a promising compound for the treatment of hematological malignancies." (PMID 23861714, 2013). "The mTOR signaling pathway has been found to be frequently deregulated, especially in a wide range of hematological malignancies." (PMID 23861714, 2013). "Our results indicate that inhibiting the IGF1R-Akt-mTOR signaling cascade is a new cellular mechanism of shikonin strengthening its potential for the treatment of hematological malignancies." (PMID 23861714, 2013). "Through the last years it has become clear that mTOR pathway contributes to the pathogenesis of hematological malignancies by playing a key role in the regulation of many cell functions, such as cell proliferation, cell growth, and angiogenesis." (PMID 21822434, 2012). "This subclass of ATP-competitive mTOR inhibitors includes several molecules which have been applied in preclinical models in hematologic malignancies." (PMID 21822434, 2012). "In fact, efforts to combine metformin with mTOR inhibitors for the treatment of solid tumors are already underway and similar studies in Ph+ leukemias and other hematological malignancies are probably warranted from the emerging experimental evidence." (PMID 22249159, 2011). "The PI3K-Akt pathway is upstream to mTOR, and the mTOR inhibitor rapamycin is used for immunosuppression after allotransplantation and is also being investigated as an anticancer agent in hematologic malignancies." (PMID 22046566, 2011). "The mTOR pathway is aberrantly activated in many hematologic malignancies, including some forms of NHL and HL." (PMID 21092307, 2010). "Abnormalities in the PI3K/AKT/mTOR signal pathway occurs in many solid or hematological malignancies." (PMID 19115995, 2008).
hematological malignancies (continued). "We expected JR-AB2-011 could be efficient in myeloid and lymphoid cells as the PI3K/AKT/mTOR pathway is often upregulated in hematological malignancies." (PMID 39259491, 2024). "On the other hand, targeting the PI3K/AKT/mTOR pathway may have anti-apoptotic and anti-coagulant effects in hematological malignancies, although the best strategy to inhibit this pathway remains to be elucidated." (PMID 38435444, 2023). "The mechanistic target of rapamycin (mTOR) pathway is a key regulator of various cellular functions, such as protein synthesis and cell growth, division, and survival, and is a critical event in the development of different hematological malignancies." (PMID 35655778, 2022). "Altered mTOR activity can alter HSC function and cause hematological disorders." (PMID 33788050, 2021). "In hematologic malignancies the mTOR activation, working in opposition with AMPK but in concert with other oncogenes such as Bcr-Abl, or metabolic modulators like HIF1α, contributes to confer the glycolytic phenotype by directly and indirectly regulating key glycolytic enzyme activity." (PMID 32053876, 2020). "Clinical efficacy and safety of mTOR inhibitors in hematological disease." (PMID 33489922, 2020). "Based on data presented in this review, we believe that mTOR inhibitors are becoming a trusted therapeutic in the clinical hematologist’s toolbelt and should be considered more routinely in combination therapy for the management of hematologic disease." (PMID 33489922, 2020). "Targeting the PI3K/AKT/mTOR signaling pathway, a central signaling center of cellular growth and survival, may have pro-apoptotic and anti-proliferative effects on hematological malignancies." (PMID 26919107, 2016). "However, the mechanisms behind EtOH-based regulation of mTOR components, mTORC1 and mTORC2, and their functional consequences in hematological malignancies are poorly understood." (PMID 25849580, 2015). "Exploiting aberrant mTOR signaling in leukemias and other hematological malignancies may indeed provide a reliable basis to preferentially enlarge malignant cells under physiological conditions." (PMID 26490657, 2015). "Despite population studies showing that the consumption of EtOH has a protective effect against hematological malignancies, the mechanisms behind EtOH’s modulation of mTOR activity in cells and its downstream consequences are largely unknown." (PMID 25849580, 2015). "The consistent demonstration of oncogenic abnormalities in the PI3K/mTOR signaling pathway and in cross-talk pathways demonstrates a clear rationale for development of signal transduction inhibitor-based approaches for children with hematologic malignancies." (PMID 24904824, 2014). "PI3K/Akt/mTOR inhibitors in clinical trials for hematologic malignancies." (PMID 24904824, 2014). "However, one factor potentially limiting the effectiveness of rapalogs for treating hematological malignancies is the fact that in vitro exposure to mTOR inhibitors often only induces G1/S cell cycle arrest without apoptosis." (PMID 23533410, 2013). "Many clinical trials have been launched to test the efficacy of mTOR inhibitors as single agents, particularly in the treatment of relapsed hematological diseases (eg. everolimus for relapsed/refractory NHL – phase I; sirolimus for relapsed/refractory ALL/NHL – phase I)." (PMID 23573198, 2013). "Activation of the phosphatidylinositol 3-kinase (PI3K)/protein kinase B (Akt)/mammalian target of rapamycin (mTOR) signaling pathway contributes to the proliferative advantage of malignant cells and may confer resistance to chemotherapy in various hematologic malignancies." (PMID 24904824, 2014). "However, an increasing number of reports indicate that activation of mammalian target of rapamycin (mTOR) signaling pathway may contribute to GC resistance in hematological malignancies." (PMID 21083937, 2010).
hematological malignancies (continued). "These inhibitors were selected based on their previously reported efficacy in hematological malignancies to explore their potential synergistic effects blocking the Hedgehog and PI3K/Akt/mTOR pathways simultaneously." (PMID 41439992, 2025). "Additionally, the modulation of pathways such as Akt, mTOR, and tyrosine kinases, as well as other key signaling pathways like Notch, Wnt, and Hedgehog, underscores the complexity and context-dependent roles of autophagy in hematological malignancies and solid tumors." (PMID 40227235, 2025). "We tested several PI3K, AKT and MTOR inhibitors, most of which are FDA-approved or in clinical trials for the treatment of hematological malignancies or solid tumors, in the human B-ALL cell lines RCH-ACV, 697, REH and SEM." (PMID 35794338, 2022). "PLK1 has central roles in the transition from G2 to M-phase and is considered a proto-oncogene because it activates the PI3K/Akt/mTOR signaling pathway in ALL and other hematological malignancies." (PMID 35445848, 2022). "Isoform-selective PI3K inhibitors demonstrate improved specificity and reduced toxicity over dual PI3K/ mTOR and pan-PI3K inhibitors, which have shown promising success in several clinical trials for both solid and hematological malignancies." (PMID 30782187, 2019). "In many cell lines inhibition of mTOR by NAMPT inhibitors leads to induction of autophagy and caspase cleavage to induce apoptosis, mainly in hematological malignancies." (PMID 29156703, 2017). "Several rapalog mTOR inhibitors, including rapamycin, temsirolimus (CCI-779), and everolimus (RAD001), have shown preclinical potential in hematological malignancies." (PMID 23533410, 2013). "NF-κB and mTOR, downstream components of the PI3K/Akt pathway, are thought to function importantly in maintenance of hematologic malignancies." (PMID 22607709, 2012). "To date, PTBP2, TMEM51, and MTOR have been found as fusion partners of KAZN by RNA sequencing studies in solid tumors, while, as far as we know, rearrangements of KAZN have never been described in hematological malignancies." (PMID 34859285, 2022).
adenocarcinoma (41 papers, 2012 to 2025). A common cancer characterized by the presence of malignant glandular cells. "Aberrant activation of PI3K/AKT/mTOR pathway is one of the mechanisms of acquired resistance to EGFR-TK inhibitors in patients with adenocarcinoma carrying EGFR activating mutations." (PMID 33997043, 2021). "A majority of lung cancers have high levels of mTOR pathway activation, and phosphorylation of S6K is associated with metastasis and poor survival in adenocarcinoma." (PMID 30359271, 2018). "Furthermore, AKT2 and AKT3, as part of phosphoinositide 3-kinase (PI3K)/AKT/mTOR signaling pathway, have been associated with several adenocarcinomas." (PMID 36982700, 2023). "We then wondered whether expression of hamartin, p-mTOR or p-TSC2 was associated with EGFR-mutations since approximately 20% of adenocarcinoma of the lung patients’ specimens reveal EGFR-mutations." (PMID 24593867, 2014). "Emerging data support the use of immune checkpoint inhibitors in squamous BGC and targeted agents (e.g., mTOR/CDK4/6 inhibitors) in adenocarcinoma." (PMID 41375020, 2025). "RICTOR amplification has been described in 10% of NSCLCs, and mutations in the tumor suppressor genes PTEN and STK11, which are negative regulators of mTOR signaling, have also been observed in squamous cell and adenocarcinomas." (PMID 38515456, 2024). "Increased p-mTOR, p-S6, and Rictor protein expressions were observed in more than 30% of primary adenocarcinomas and around 70% of brain metastases." (PMID 38515456, 2024). "We also showed increased activation of mTOR signaling in the adenocarcinoma tissue of CRC with a strong positive correlation to metastasis." (PMID 39337548, 2024). "In contrast, phosphorylation of mTOR and NFκB signaling were increased in the adenocarcinoma tissue of CRC (p < 0.05)." (PMID 39337548, 2024). "In line, CDDP-resistant H460, H1975 and mouse adenocarcinoma cells all displayed strongly elevated mTOR signaling, characterized by phosphorylation of mTORC1 target sites (p70S6KT389, 4E-BP1T37/46, and ULK1S757) and increased expression of FancD2." (PMID 32943635, 2020). "In a recent study by Chen and colleagues, nine subtypes of NSCLC were characterized, and for adenocarcinoma three subtypes showed significant increases in p38 and mTOR pathway activation." (PMID 30359271, 2018). "p-mTOR was expressed in most adenocarcinomas (ACs) analyzed, including those derived from the stomach, colon, pancreas, and lung." (PMID 28831205, 2017). "As for a potential downstream regulation of mTOR, this is more frequent in adenocarcinoma (90%)." (PMID 40676628, 2025). "Of note, a paired genomic analysis proposed, in a single center study, that an acquired genomic alteration in LKB1 through activation of the PI3K/AKT/mTOR pathway might favor the adenocarcinoma to squamous cell transformation after EGFR-TKIs." (PMID 36661676, 2022). "Dysregulation of the mTOR pathway is more common in squamous lung carcinoma than adenocarcinoma." (PMID 28208579, 2017). "The staining intensities for p-mTOR and p-S6 were weaker compared to those in AAHs and adenocarcinomas, which might reflect less aggressive behavior." (PMID 26974543, 2016). "Intriguingly, the mTOR/glycolysis combined pathway score was significantly lower in NEPC compared to adenocarcinoma, suggesting that this metabolic dysregulation may represent a distinct mechanism of aggressive disease from the transition to the androgen‐independent NEPC phenotype." (PMID 39985777, 2025). "Intensified in adenocarcinoma tissue, proliferation (marked by Ki67) positively correlated with the stage and metastasis of CRC (marked by mTOR)." (PMID 39337548, 2024). "We provide an extensive characterization of ‘105C’, a cell line generated from an adenocarcinoma of the clear cell histotype using targeted next-generation sequencing, cytogenetic microarrays, along with analyses of AKT/mTOR signaling." (PMID 33153119, 2020).